PNMA1 (PNMA family member 1)
Synonyms: MA1
Tractability: PROTAC: ubiquitination databases record sites on it.
Gene: Protein-coding gene on chromosome 14 (73,711,783 to 73,714,384, reverse strand). Ensembl gene ENSG00000176903.
Subcellular location: Nucleus, nucleolus
Subcellular location (Human Protein Atlas): Cytosol; Nucleoplasm
Gene Ontology:
Molecular function: protein binding
Biological process: inflammatory response to antigenic stimulus; positive regulation of apoptotic process
Cellular component: cytoplasm; nucleolus
Genetic constraint (gnomAD): Loss-of-function variants: 21 observed, 26.87 expected, observed/expected ratio (o/e) 0.78, 90% interval 0.55 to 1.12. The upper end of that interval is the gene's LOEUF score, 1.12, which puts it in group 4 of 6, group 1 being the genes least tolerant of losing a copy. Missense variants: 435 observed, 463.87 expected, observed/expected ratio (o/e) 0.94, 90% interval 0.87 to 1.01. Synonymous variants: 189 observed, 189.04 expected, observed/expected ratio (o/e) 1, 90% interval 0.89 to 1.13.
Homologues: Orthologues: chimpanzee PNMA1 (100% identical), macaque PNMA1 (99% identical), dog PNMA1 (97% identical), pig PNMA1 (96% identical), rat Pnma1 (94% identical), mouse Pnma1 (92% identical), guinea pig PNMA1 (91% identical). Paralogues in human: MOAP1 (58% identical), PNMA2 (48% identical), PNMA3 (48% identical), PNMA5 (45% identical), PNMA6A (43% identical), PNMA6F (38% identical), PNMA6E (37% identical), PNMA8A (29% identical), ZCCHC18 (25% identical), ZCCHC12 (25% identical), PNMA8B (21% identical), CCDC8 (18% identical), and 1 more.
Diseases named in the same sentence as PNMA1 in open-access papers:
PNMA1 is named in the same sentence as 34 diseases in open-access papers, as found by Europe PMC text mining. Sharing a sentence is not in itself a finding about the gene and the disease. The quoted sentences say what the papers report.
paraneoplastic neurological syndrome (5 papers, 2017 to 2024). "PNMA1–3 were originally identified as targets of the autoantibodies that cause paraneoplastic neurological syndrome (PNS) in lung and gynecologic cancers." (PMID 39041030, 2024). "PNMA1 falls under the family of proteins implicated in an autoimmune disorder called paraneoplastic neurological syndrome." (PMID 36593453, 2023). "Paraneoplastic Ma1 (PNMA1) is a member of an expanding family of “brain/testis” proteins thought to be involved in an autoimmune disorder defined as paraneoplastic neurological syndrome." (PMID 33008022, 2020).
melanoma (2 papers, 2020 to 2025). A malignant, usually aggressive tumor composed of atypical, neoplastic melanocytes. "Till date, there is no literature on the role of PNMA1 in melanoma or UM." (PMID 33008022, 2020).
Obesity (2 papers, 2021 to 2024). Accumulation of substantial excess body fat. "Analysis of donated human ovaries shows that expression of both genes declines normally with age, while several PNMA1 and PNMA4 variants identified in genome-wide association studies are causally associated with low testosterone, altered puberty onset, or obesity." (PMID 39041030, 2024).
ovarian carcinoma (2 papers, 2021 to 2024). A malignant neoplasm originating from the surface ovarian epithelium. "Moreover, we found that PNMA1-ChgA double positive cells were significantly amplified in the ovarian carcinoma tissues." (PMID 39592661, 2024). "Of note, PNMA1 is present in both SKOV3WT and SKOV3CP ovarian carcinoma cells and was enhanced in cisplatin-exposed cells, as corroborated using different methods." (PMID 39592661, 2024). "This neuronal or epithelial signature of ovarian carcinomas is raised from a rare cell type found in regular (non-tumoral) ovarian tissues which have a particular phenotype expressing Tyrosine hydroxylase, ChgA, the paraneoplastic protein PNMA1 and KRT80." (PMID 39592661, 2024).
breast carcinoma (1 paper, 2020). "Although increased PNMA1 expression and its protein levels have been shown to be proapoptotic in neurons, they have been found to play a prosurvival and antiapoptotic role in pancreatic, gastric, and breast cancers." (PMID 33008022, 2020).
cerebellar ataxia (1 paper, 2024). A neurological syndrome characterized by clumsy and uncoordinated movement of the limbs, trunk, and cranial muscles. "These anti-PNMA1-autoantibodies cross-react with the nervous system structures inducing vast neurological impairments like limbic and extra- limbic encephalopathies, Bergmann gliosis, cerebellar ataxia, etc." (PMID 39592661, 2024).
dementia (1 paper, 2019). Loss of intellectual abilities interfering with an individual's social and occupational functions. "Anti-PNMa1 autoantibodies can be found in patients with paraneoplastic neurological disorders in connection with brainstem or limbic encephalitis, hypothalamic disorder and dementia." (PMID 30876387, 2019).
pancreatic cancer (1 paper, 2018). "Furthermore, Chen and colleagues found that PRELP, LGALS1 and RPS8 might be significant prognostic factors for pancreatic cancer, while another study showed that PNMA1 was associated with prolonged overall survival and might serve as a prognostic biomarker for pancreatic cancer." (PMID 29515771, 2018).
tumor (9 papers, 2014 to 2026). "However, the biological and clinical significance of PNMA1 in tumours is poorly understood." (PMID 33008022, 2020). "Decisively, we also found that those cell populations in “regular” (non-tumoral) ovarian tissues, which are dually PNMA1-ChgA positive, are exactly the cell populations that are expanded to form the tumor bulk." (PMID 39592661, 2024).
cancer (5 papers, 2017 to 2026). A tumor composed of atypical neoplastic, often pleomorphic cells that invade other tissues. "Of note, patients suffering from different types of cancer, develop an antibody-mediated immune response triggered by the PNMA1 antigen, a 37-kDa protein restricted to neurons, testis cells and cancer cells." (PMID 39592661, 2024).
PNMA1 also shares sentences with these, for which no sentence is quoted: infection (6 papers); autoimmune disorder (2); hepatocellular carcinoma (2); Abdominal obesity (1); acute monocytic leukemia (1); autoimmune encephalitis (1); colon cancer (1); encephalitis (1); gastric cancer (1); Hepatic steatosis (1); hypothalamic disorder (1); influenza (1); ischemic disease (1); lung carcinoma (1); neurological disorders (1); Opsoclonus (1); prostate carcinoma (1); rectal cancer (1); seminoma (1); testicular cancer (1); testicular seminoma (1); Thromboembolism (1); thrombotic disease (1); tuberculosis (1).